IL6 (interleukin 6)
Diseases named in the same sentence as IL6 in open-access papers (continued):
Sharing a sentence is not in itself a finding about the gene and the disease.
infection (continued). "High IL6 level linked with phosphorylated STAT3 level, poor liver function, variceal severity, and patients' mortality in cirrhotic patients caused by HBV‐ and HCV‐infection." (PMID 31219249, 2019). "Notably, IL-6 mRNA was induced in the cerebral cortex of infected WT mice on 3 and 5 day post-infection, whereas it only slightly induced in the cortex of infected TLR7-/- mice." (PMID 31730654, 2019). "The results indicate that the use of Bokashi as feed additives resulted in increased concentrations of pro-inflammatory cytokines TNF-α and IL-6, which increase the protective capacity of the colostrum by stimulating cellular immune mechanisms protecting the sow and neonates against infection." (PMID 29305686, 2019). "Interestingly, and in contrast to the aerosol/celecoxib infection model, ibuprofen treatment after i.v. infection significantly decreased lung infiltration of neutrophils as well as IL-6 (p = 0.028 and p < 0.0001)." (PMID 31396568, 2019). "Our findings suggest that lncSSBP1 may affect IL-6 mRNA expression during TM infection through interaction with hnRNPk in bronchial epithelial cells." (PMID 31998294, 2019). "These assign IL-6 an unexpected homeostatic role in limiting infection-related inflammation." (PMID 32038632, 2019). "We further blocked IL-6 and IL-8 during infection to determine whether these cytokines contributed to increased TF expression using concentrations that were showed to neutralized these cytokines." (PMID 31068911, 2019). "In the present study, IL-6 and IL-1B were proven to be induced throughout the infection process by qRT-PCR, which reinforced the hypothesis." (PMID 31130962, 2019). "In summary, IL-6 expression is down-regulated during TM infection in bronchial epithelial cells." (PMID 31998294, 2019). "In a sub-lethal challenge with these viruses, our quantitative PCR analysis of the infected spleens and lungs showed only a transient upregulation of IL1B and IL6 mRNA on the first day post-infection, which returned to control levels by the second or third day." (PMID 30634569, 2019). "While kidney levels of TNF-α, IL-6, and IL-10 were significantly increased on the third day after infection, the levels of IL-1, IL-12p40, and IL-12p70 were significantly reduced on the sixth day after infection in A/J C5−/− mice when compared to A/J C5+/+." (PMID 31687410, 2019). "Moreover, apoptosis induction, tight junction redistribution, and an increased inflammatory response—represented by TNF-α, IL-1β, and IL-6 secretion—was observed in co-cultures after infection and reversed by curcumin." (PMID 31569415, 2019). "In the presence of long-standing HCV infection, which is quite common since the infection remains asymptomatic for a long time, the continued replication of the virus in the liver cells may decrease their ability to produce IL-6, and consequently CRP." (PMID 30813467, 2019). "During ADE of infection, both the IL-10 as well as IL-6 levels are increased." (PMID 29740424, 2018). "Thus, MDSCs have the ability to shift the balance of soluble mediators at the site of infection toward suppressive and regulatory cytokines, by releasing high amounts of IL-10 and IL-6." (PMID 30405617, 2018). "However, no studies to date have examined the effects of repeated exposure to common infections on circulating IL-6 and CRP levels in children, which are typical markers of chronic, low-grade systemic inflammation." (PMID 29198208, 2018). "Furthermore, even when miR‐223 expression is strongly suppressed by miR‐223 AS ODN, if PGN stimulation (S. aureus recognition) is received, positive feedback occurs; thus, through increased IL‐6 production, infection control becomes more effective." (PMID 30171089, 2018). "Both RGV and ADRV infection induced the up-regulation of cytokines at 1 dpi, such as IL6, IL8, TNFα, and CD114, which could benefit the neutrophil formation and proinflammatory and chemotactic effects." (PMID 29558886, 2018).
infection (continued). "However, following infection, we observed significantly elevated levels of IL-1β, IL-2, IL-3, IL-5, IL-6, IL-10, IL-17A, MIP-1α, MIP-1β, KC, transforming growth factor β (TGF-β), G-CSF, and GM-CSF in HO-1−/− mice compared to HO-1+/+." (PMID 30428359, 2018). "In response to brain injury and infection, neuro-inflammation triggers microglia to attain an activated state, leading to the release of pro-inflammatory cytokines such as tumor necrosis factors α (TNFα), interleukin-6 (IL-6) and IL-1β." (PMID 29484176, 2018). "Furthermore, HSV-2 + Cc-A1AT produced significantly more IL-6 at 4 hours post-infection than HSV-2 alone." (PMID 29434285, 2018). "Finally, we repeated the analyses testing between infection burden and IL-6/CRP after re-categorising the infection burden variable into quartiles." (PMID 29198208, 2018). "Moreover, Mincle−/− mice exhibit significantly higher P. murina burdens with elevated levels of TNF-α, IL-6, and IL-1Ra during infection, indicating that Mincle functions as an important signaling receptor in host defense against Pneumocystis infection." (PMID 29915598, 2018). "In fact, IL-6 is considered a biomarker of virulence during the infection with these viruses." (PMID 30158915, 2018). "Also active in the infection are lipoproteins that have been shown to react with Toll-like receptor 2 to induce both cytokines (IL-6 and IL-8) and antibacterial molecules." (PMID 29320451, 2018). "Also, by using specific inhibitors against ERK1/2, p38, and JNK, we observed that inhibition of all three MAPK pathways significantly decreased the infection-induced upregulation of proinflammatory cytokines IL-6, IL-8, IL-Iβ, and TNF-α." (PMID 30340642, 2018). "Indeed, there was a statistically significant increase in serum IL-6 levels over the course of infection, with this being mitigated in the AAS group in later stages." (PMID 29740435, 2018). "Here, the infection induced by Pb18 caused augmented production of IL-10 and IL-6 by the lung tissue of infected animals from the nondiabetic groups." (PMID 30426021, 2018). "Additionally, IL‐6 was higher in the normal group and lower in the 7‐week post‐infection group than their controls." (PMID 29577333, 2018). "Surprisingly, sublethal infection with either Pmt2-expressing or Pmt2-deficient yeast cells did not change core body temperatures, despite the production of fever-inducing cytokines (e.g., tumor necrosis factor alpha [TNF-α], interleukin-1β [IL-1β], and IL-6) after infection." (PMID 29295913, 2018). "IL-6 is also essential for maturation of activated B cells into immunoglobulin-producing cells, promoting T follicular helper cell (Tfh) generation for viral control in the late stages of infection." (PMID 30091725, 2018). "Furthermore, fibrillarin knockdown prior to infection led to a reduction of pro-inflammatory cytokines interleukin (IL)-6 and IL-8, and an induction of anti-inflammatory cytokine IL-10 indicative of reduced inflammation." (PMID 30190478, 2018). "Thus, IL-6 regulates, amongst others, acute phase responses and liver regeneration, resulting in dramatically increased IL-6 serum levels upon states of infection, inflammation, and liver damage." (PMID 30591653, 2018). "When we further analyzed the phenotype of freshly isolated aged KC, we observed an increase in the inflammatory cytokine IL‐6, a key driver of liver regeneration, infection defense, and regulation of metabolic functions without changes in the mRNA expression of other inflammatory molecules." (PMID 30260562, 2018). "At six d.p.i., MHV68/IL6 showed significantly more soluble type I collagen in BAL fluid than WT MHV-68 infection; by nine d.p.i., soluble type I collagen was significantly higher in BAL fluid from both WT and MHV68/IL6 infection in comparison to the uninfected control." (PMID 30486363, 2018).
infection (continued). "Interestingly, MitoQ treatment prior to direct TC-83 infection of microglia corresponded with increased IL-6 and IL-8, while treatment with BAY-82 in both direct and indirect infection scenarios led to increased levels of all cytokines queried." (PMID 30101649, 2018). "hMPV-GFP infection (as measured by GFP expression) was also inhibited by IL-6." (PMID 29441069, 2018). "Although IL-6 is another key cytokine required for protection from primary Lm infection, we observed lower levels of systemic IL-6 following heterologous Lm-gp61 challenge, as compared to primary infection." (PMID 29438281, 2018). "Lower levels of IL-6 in DWS patients may reflect that these patients might be sampled after few days of infection when IL-6 levels tend to drop followed by an increase until when shock occurs." (PMID 30112159, 2018). "In vitro and in vivo models of infection have shown that anthropophilic species (including Trichophyton tonsurans) induce keratinocytes to secrete a limited spectrum of cytokines, mainly IL-8, IL-6, and IL-1β." (PMID 29896175, 2018). "In contrast, IL-6 levels were equally increased at day 7 after infection in WT and PI3Kγ KO mice." (PMID 29867955, 2018). "Most importantly, loss of TRIM28 S473 phosphorylation by inhibition of p38 and MSK1 also resulted in decreased levels of IFN-β, IL-6, and IL-8 during infection with SC35M, which was not caused by an inhibition of viral replication." (PMID 30323812, 2018). "Severe IV infection induces many cytokines; IFNαβ, TNFα, IFNγ, C-X-C motif chemokine (CXCL) 10 (CXCL10), CXCL9, C-C motif ligand (CCL) 2 (CCL2), CCL4, CCL5 and interleukin (IL)−6 (IL-6), IL-2, IL-8, and IL-10 have all be observed to be upregulated during severe IV infection in humans." (PMID 30250466, 2018). "Control of infection depends on classical IL-6 signaling via membrane IL-6Rα, but IL-6 target cells and protective mechanisms remain unclear." (PMID 30169526, 2018). "Cells infected with the Dengue virus produce nitric acid and protective pro-inflammatory cytokines such as Interferon-gamma (IFN-γ), Tumour Necrosis factor-alpha (TNF-α), interleukin-6 (IL-6) and IL-10 to attract and activate leucocytes at the site of infection." (PMID 30112159, 2018). "IL-6 controls neutrophil maturation and recruitment to sites of infection." (PMID 30169526, 2018). "At 24 hours after infection, serum levels of Il-6, IL-17, IL-10, TNFα and IL1β were unchanged and while the levels of Il-6, IL-10, TNFα and IL1β increased in Ddx3xfl/y Vav-iCre relative to control animals at 72h, the difference only reached significance in the case of IL-10." (PMID 30475900, 2018). "This may indicate that in T cells stimulated by LEC+, other factors in addition to IL-6 are playing a role in infection, which is consistent with our findings in IL-6 blocking experiments." (PMID 30285810, 2018). "through an effect on the target cells, we investigated whether the HeLa cells released inflammatory mediators, such as IL-6 and IL-8, upon infection with bacteria." (PMID 30136243, 2018). "In addition, we found (several) complementary myeloid cell populations serving as hematopoietic sources of IL-1, IL-6 and/or IL-23 during infection." (PMID 29782555, 2018). "During infection by the C. glabrata reference strain, ocular IL-6 and MCP-1 were positively correlated with ocular fungal burden; however, the concentrations of these mediators were low and not detected in most infected mice, indicating only mild inflammation induced by C. glabrata." (PMID 30386320, 2018). "Perinatal mortality calves with diagnosed infection in utero were posited in hypothesis two to have higher concentration of IL-6, as human fetuses with diagnosed infection in utero showed elevated IL-6 concentrations." (PMID 30382887, 2018).
infection (continued). "Similarly, ZIKA virus (ZIKV) infection induces pY705 in primary retinal glial cells and favors the activity of the IL-6/STAT3 pathway in blood mononuclear cells from infected rhesus monkeys, albeit without any known molecular mechanism." (PMID 29543893, 2018). "Next, we probed for IL-6-induced antiviral effects on hMPV-GFP infection." (PMID 29441069, 2018). "Once we knew IL-6 is involved in EC and LEC stimulation of resting CD4+ T cells, we set out to measure IL-6 levels at the end of infection (day 6 post infection) in T cells co-cultured with EC or LEC using ELISA, to see if IL-6 levels correlated with infection levels." (PMID 30285810, 2018). "Furthermore, we reveal a positive feedback loop between Notch signaling and Janus kinase (JAK)/STAT3 pathway during in vitro infection that involves Notch-boosted IL-6." (PMID 30042932, 2018). "It has been demonstrated that IL-6 can be produced by infected resident macrophages and act on the endothelium and PBMCs to stimulate the production and release of chemokines to attract more phagocytes to the site of infection." (PMID 30627118, 2018). "IL-17A is known as an inflammatory cytokine whose main function is exerted on myeloid and mesenchymal cells by inducing the expression of granulocyte colony-stimulating factor (G-CSF), IL-6, and other chemokines, which increase granulopoiesis and recruit neutrophils into the site of infection." (PMID 29805810, 2018). "Additionally, infection with a miR-US5-1/miR-US5-2/miR-UL112-3p triple miRNA mutant virus resulted in significantly increased secretion of IL-6 compared to wild type infection." (PMID 30360396, 2018). "Furthermore, significantly reduced IL-6, CCL20, and hBD2 expression along with CXCL8 and CCL20 secretion by RHE were observed at 16 h post-infection using T3SS deficient strain." (PMID 30070169, 2018). "Reduced secretion of IL-6 during antigen presentation may lead to development of CD4+ Th2-dependent response which is important during infection of mucous membranes." (PMID 29872440, 2018). "IL-6 has shown the best sensitivity for predicting infection in patients with preterm labour." (PMID 29434245, 2018). "The concentration of IL-6 was significantly increased by 12 dpi, peaked at 20 dpi and decreased afterwards whereas the concentrations of IL-1β and IL-2 remained unchanged along the infection." (PMID 30455700, 2018). "It has been reported that IL-6 may be involved in the infection process of MP and play an important role in the pathogenesis of MP pneumonia." (PMID 30305831, 2018). "While proinflammatory cytokines such as TNF-α and IL-6 are distributed early on during the acute stage of an injury or tissue infection, chemokines like R/C may be activated at a later time." (PMID 30174768, 2018). "MoDCs derived from Donor B also produced high levels of IL-6 after mock infection." (PMID 30401896, 2018). "Many reviews of molecular profiling strategies have highlighted the importance of analyzing molecular data in conjunction with other clinical measures of severity (i.e., APACHE, SOFA scores), markers of infection (i.e., procalcitonin), and markers of inflammation (i.e., IL-6, IL-10)." (PMID 30045694, 2018). "Although HSV-2 + Cc-BmKn2 did cause a slight elevation in IL-6 at 4 hours post-infection, this was not statistically significant." (PMID 29434285, 2018). "For example, C. neoformans infection was exacerbated in IL-6−/− and IL-12−/− mice, confirming the hypothesis that Th17 and Th1 responses are involved in natural resistance to infection and the induction of a protective response." (PMID 30401972, 2018). "Thus, EVs from L. amazonensis appear to stimulate the production of IL-6 to attract more phagocytes to the site of infection and to simultaneously induce the production of IL-10 to deactivate the microbicidal effects of recruited cells." (PMID 30627118, 2018).
infection (continued). "We found rises in IFN-gama, TNF-alpha and IL-6 at 9 day after infection in all infected groups as compared to uninfected mice but only Bz displayed statistically significant lower (p = 0.02) TNF-alpha levels, possibly due to reduced parasitism levels and respective antigenic stimuli." (PMID 30186314, 2018). "The overall pattern of association between infection burden and IL-6/CRP was similar between groups with and without atopic disorders." (PMID 29198208, 2018). "In addition, IL-6 promotes differentiation of granulocytic MDSCs, and the number of monocytic MDSCs increases when IL-6 production is enhanced due to infection by hepatitis B virus." (PMID 29456539, 2018). "Upon infection, TLRs recognized pathogens and resulted in the phosphorylation and degradation of IκB; then NF-κB is free to translocate into the nucleus and promote the expression of many inflammatory mediators, such as IL-1β and IL-6." (PMID 29681986, 2018). "Moreover, the secretions of TNF-α and IL-6 in culture supernatants after Mab infection were also decreased by pretreatment with SdLv in a concentration-dependent manner." (PMID 30452471, 2018). "IL-6 plays a central role in the response of regulatory T cells to microbial infections, and is known to be a predominant mediator of the acute phase response in inflammation triggered by infection." (PMID 30064361, 2018). "Thus, in the case of hMPV-GFP and in contrast to EHDV-TAU, the infection-restricting effect of IL-6 was dependent on cell death." (PMID 29441069, 2018). "We started by studying the interplay of hypoxia and infection on the secretion of IL-6 and TNF-α." (PMID 30463908, 2018). "Moreover, CARD9 deficiency completely blocked AM accumulation and significantly reduced secretion of pro-inflammatory cytokine including TNF-α and IL-6 in the lungs on day 1 after infection with C.g-B." (PMID 30131805, 2018). "Indeed, the protease inhibitor A2MP is induced in MHV68/IL6 infection, consistent with higher type I collagen deposition." (PMID 30486363, 2018). "Importantly, such an effect was not demonstrated for IL-1α, TNFα, or interferon γ, suggesting a key role for IL-6 in mediating the neurobehavioral consequences of infection for the offspring." (PMID 30344483, 2018). "IL-6, an inflammatory cytokine secreted by immune cells such as T-cells, monocytes, macrophages, and synovial fibroblasts, is increased in humans following stimulation by inflammation, infection, and external injuries." (PMID 29713361, 2018). "However, during chronic infection with LCMV Clone 13, a second wave of IL-6 expression is observed 3 weeks post-infection." (PMID 30405612, 2018). "SP600125 also decreased the level of caspase-3 and IL-6 induced by infection." (PMID 29681986, 2018). "In contrast to infection with rgRSV, IL‐6 and IL‐8 mRNA levels were much stronger elevated in the presence of poly(I:C), possibly indicating anti‐inflammatory mechanisms mediated by RSV predominantly in H441 cells, as the inflammatory outcome in IMR‐90 cells was more pronounced." (PMID 29660819, 2018). "IL-6 levels in control mice at 3 days post-infection exceeded those of asthmatic mice at this time point (p = 0.015), and peaked to 1696.8 pg/mL at 7 days post-infection." (PMID 28831046, 2017). "Furthermore, the infection of primary cultured microglia with P. gingivalis also significantly increased the secretion of IL-6 and TNF-α, and the accumulation of NO metabolites." (PMID 28924232, 2017). "Infection with S. aureus 6850 resulted in marginal production of IL-6." (PMID 28195157, 2017). "We also measured cytokine production after C. albicans restimulation of splenocytes obtained from 2-DG or BPTES-treated mice after the infection, finding a significant reduction in the production capacity of IL-1β, IL-6, IL-10, TNFα and IFNγ in mice treated with 2-DG." (PMID 28922415, 2017). "As a control of BMDM infection, Il6 expression strongly increased during ST infection." (PMID 28507548, 2017).